PCSK9 (proprotein convertase subtilisin/kexin type 9)
Diseases named in the same sentence as PCSK9 in open-access papers (continued):
Sharing a sentence is not in itself a finding about the gene and the disease.
myopathy (10 papers, 2016 to 2025). A disease of the muscle in which the muscle fibers do not function properly. "Many trials have revealed that PCSK9 inhibitors have reduced all causes of mortality including cardiovascular mortality with less adverse effects like myopathy and hepatotoxicity." (PMID 29770231, 2018). "Statin-induced PCSK9 increase may partially explain the limitation to reach therapeutic targets and the need to progressively augment statin dose at the expense of increased risk of myopathies." (PMID 28704936, 2017). "Patient 7 was treated with ezetimibe and subsequently with a PCSK9 monoclonal antibody (alirocumab) due to statin-induced myopathy and complete statin intolerance." (PMID 41303093, 2025). "One solution is addition of PCSK-9 inhibitor, but this road is fraught with problems and often requires prior authorization or non-approval by insurance plans even with clear evidence of classic stain-induced myopathy." (PMID 36060284, 2022). "Statins and PCSK9 inhibitors may cause adverse effects in some patients, including myopathy and hepatic dysfunction, and are not uniformly effective across patient populations." (PMID 41182513, 2025). "Notably, agents like bempedoic acid and proprotein convertase subtilisin/kexin type 9 (PCSK9) inhibitors (evolocumab, alirocumab, inclisiran) have emerged as effective options to intensify LLT and achieve LDL-C goals, addressing limitations associated with statins, such as myopathy." (PMID 38592091, 2024). "Non-statin lipid-lowering therapies, such as ezetimibe or PCSK9 inhibitors, may be considered, with close monitoring for myopathy recurrence." (PMID 41384183, 2025).
neurodegenerative disease (10 papers, 2019 to 2026). A disorder of the central nervous system characterized by gradual and progressive loss of neural tissue and neurologic function. "Cerebral spinal fluid (CSF) PCSK9 concentrations are correlated with neural tube defects and neurodegenerative diseases in human patients." (PMID 32595449, 2020). "In that respect, PCSK9 concentrations were found higher in the cerebrospinal fluid as well as brain autopsies of AD patients compared with controls, but similar observations have been made for other neurodegenerative diseases." (PMID 37586604, 2023). "Overall, as an important modulator of lipid homeostasis, it is possible that PCSK9 plays a role in neurodegenerative diseases, but at present this role remains unclear." (PMID 35323658, 2022). "As such, several studies have been conducted to explore the potential role that PCSK9 may have in the progression of neurodegenerative diseases." (PMID 35323658, 2022). "However, the effects of PCSK9 inhibitors on neurodegenerative diseases are controversial." (PMID 38837845, 2024). "Research has shown that proprotein convertase subtilisin/kexin type 9 (PCSK9) inhibitors, particularly SBC-115076, have a protective effect against various neurodegenerative diseases." (PMID 39157774, 2024).
bacterial infection (8 papers, 2012 to 2024). "It has been reported that an inappropriate induction of PCSK9 upon bacterial infection was associated with mortality." (PMID 37515197, 2023). "Therefore, PCSK9 inhibitors were considered promising candidates for the pathogenic bacterial infection." (PMID 33123601, 2020). "Additional pleiotropic effects of PCSK9 inhibitors, including plaque stabilization, anti-atherosclerotic effects, antineoplastic effects, and the ability to impact the course of bacterial infections, have been comprehensively reviewed recently." (PMID 35566668, 2022). "This principally argues against systemic PCSK9 levels as a marker of bacterial infections." (PMID 37515197, 2023). "Besides addressing the impact of adipokines on hepatic PCSK9 levels in various disease settings, researchers have also examined if hepatic PCSK9 expression is modulated by inflammatory mediators, such as exposure to lipopolysaccharide (LPS) after bacterial infection." (PMID 35162992, 2022). "An equal rise in plasma PCSK9 in Gram-negative and Gram-positive blood infections has been shown before, and therefore, higher PCSK9 levels may be a marker of severe illness rather than for bacterial infections." (PMID 37515197, 2023). "Since there are no data on PCSK9 levels and antibiotic resistance or the severity of disease in patients with bacterial infections in intensive care units, the aim of this study was to investigate whether any such associations exist." (PMID 31635200, 2019).
vasculopathy (8 papers, 2017 to 2025). "High PCSK9 concentrations in plasma have been associated with vascular disorders." (PMID 36294964, 2022). "Altogether, these data suggest that Pcsk9 depletion attenuates allograft vasculopathy in a mouse model of GVD." (PMID 35720337, 2022). "Here, we found that Evolocumab, similar with Pcsk9 knockout, reduced allograft vasculopathy in hPCSK9 mice." (PMID 35720337, 2022). "Rs7575840 in 6.5kda upstream of ApoB gene, rs11591147 in PCSK9 gene and rs9644862 in the CDKN2B-AS1 (or named ANRIL; p15AS; PCAT12; CDKN2BAS; CDKN2B-AS; NCRNA00089) gene were illustrated to mostly influence the risk of intestinal vascular diseases." (PMID 39991491, 2025). "Considering an early initiation of combination therapy with a low-/moderate-intensity statin and ezetimibe, novel parenteral PCSK9 modulators and BA can provide safe and efficient lipid management, translating into a decrease in the rate of CV events, allograft rejection and vasculopathy." (PMID 40575919, 2025). "In addition, Pcsk9 knockout (Pcsk9-/-) mice were tested for their development of graft vasculopathy compared to the wild-type (WT) mice." (PMID 35720337, 2022). "In addition, Pcsk9 knockout inhibits NLRP3 inflammasome signaling in VSMCs and reduces allograft vasculopathy." (PMID 35720337, 2022).
inflammation (7 papers, 2019 to 2025). Aberrant reaction of the microcirculation characterized by movement of fluid and leukocytes from the blood into extravascular tissues. "A comparative study is necessary to confirm the differences in HFD-induced chronic liver inflammation by using PCSK9 knockout and hepatic PCSK9 knockdown animal models." (PMID 39963241, 2025). "Proprotein convertase subtilisin/kexin type 9 (PCSK9) is related to vascular inflammation and detected in atherosclerotic plaques." (PMID 37873789, 2023). "PCSK9 may play an important role in alcohol-induced pathologies along the gut-liver-brain axis and may be a novel therapeutic target for AUD-related liver and brain inflammation." (PMID 33919550, 2021).
autosomal dominant disease (6 papers, 2014 to 2023). Autosomal dominant form of disease.
liver (5 papers, 2021 to 2025). "Further mechanistic studies are warranted to elucidate whether PCSK9 plays a causal role in autoimmune liver pathogenesis or serves as a downstream marker of immune activation." (PMID 41271978, 2025). "This suggests that serum Pcsk9 may be as a biomarker for coronary artery lesion severity and may contribute to risk stratification in PMI patients, while providing guidance for clinical application of Pcsk9 inhibitors." (PMID 34044829, 2021). "The two previous studies that measured PCSK9 in patients with UC did not report liver enzyme levels in patients with UC to exclude chronic liver injury as a confounding factor." (PMID 40265438, 2025).
nervous system disorder (5 papers, 2015 to 2026). A non-neoplastic or neoplastic disorder that affects the brain, spinal cord, or peripheral nerves. "It remains to be elucidated whether PCSK9 is associated with the development of the nervous system and neurological disorders." (PMID 26691006, 2015).
psychiatric disorder (3 papers, 2021 to 2024). A disorder characterized by behavioral and/or psychological abnormalities, often accompanied by physical symptoms. "In addition, PCSK9 inhibitors had a lower reporting probability of nervous system and psychiatric disorders compared with various statins and ezetimibe, which were seldomly investigated previously." (PMID 36506552, 2022).
retinopathy (3 papers, 2022 to 2025). "These analyses showed effects of retinopathy-associated genotypes on increased gene expression for PCSK9 (rs2479409) in skin fibroblasts, for CYP2C19*2 (rs4244285) in skin fibroblasts, liver, and stomach, and for PROX1 (rs340874) in the brain (Consortium, 2015)." (PMID 35600617, 2022).
benign tumors (2 papers, 2018 to 2025). "This study is the first to reveal an immune mechanism by which the liver modulates heart transplant rejection through the PCSK9/CD36 axis, expanding the understanding of PCSK9’s role in immunoregulation and offering a novel therapeutic target for preventing transplant rejection." (PMID 41478627, 2025).
connective tissue disorder (2 papers, 2022 to 2024). A disease involving the connective tissue. "Compared with all other drugs, PCSK9 inhibitors were associated with an increased reporting risk of musculoskeletal and connective tissue disorders and general disorders and administration site conditions, overall and by subgroups." (PMID 36506552, 2022). "When compared with statins/ezetimibe, there was no significant increased signal of “musculoskeletal and connective tissue disorders” associated with PCSK9 inhibitor." (PMID 36506552, 2022).
dorsopathies (2 papers, 2022 to 2024). "Previous studies have identified an association of PCSK9 with severe forms of dorsopathy, which we were unable to investigate in CKB, a population-based study of middle-aged adults." (PMID 38198221, 2024). "Furthermore, since estrogen competes with statins for transporters and enzymes, and female gender has previously been deemed as a risk factor for musculoskeletal disorders, PCSK9 inhibitors have the potential as a better alternative for women." (PMID 36506552, 2022). "Just as musculoskeletal disorders are more common and more likely to induce drug discontinuation in women over 65 than in younger men, it is urgent to clarify whether specific high-risk subgroups exist for PCSK9 inhibitors." (PMID 36506552, 2022).
peripheral neuropathy (2 papers, 2025). A disorder affecting the peripheral nervous system. "Our findings demonstrate that PCSK9 plays a critical role in peripheral nerves by regulating lipid homeostasis and that its deficiency results in symptoms related to peripheral neuropathy." (PMID 40338666, 2025). "One apparent limitation to the present study is that our in vivo results contrast with the fact that, over the last decade, only 1 documented case of peripheral neuropathy has been causatively linked to PCSK9 inhibitors usage." (PMID 40338666, 2025). "We found that PCSK9 deletion in mice leads to peripheral neuropathy, characterized by reduced thermal and mechanical pain sensations." (PMID 40338666, 2025). "By centering on this glial population and its link to CD36-dependent lipid entry, our article highlights a novel perspective that distinguishes it from earlier work and aims to clarify how PCSK9 may contribute to peripheral neuropathy." (PMID 41002444, 2025).
adenocarcinoma (1 paper, 2023). A common cancer characterized by the presence of malignant glandular cells. "Early adenocarcinoma may have more need for PCSK9 and cholesterol compared to advanced pathological stages." (PMID 37103355, 2023).
digestive system cancer (1 paper, 2025). A primary or metastatic malignant neoplasm involving any part of the digestive system. "We comprehensively assessed the potential impact of genetic variants related to LDL mediated by HMGCR, PCSK9, and NPC1L1 on digestive system cancers." (PMID 40443776, 2025). "After constructing the genetic instruments, we discovered that the genetic variants associated with LDL mediated by HMGCR, PCSK9, and NPC1L1 have distinct effects on digestive system cancers, and these findings were validated through meta‐analysis across two independent GWAS datasets." (PMID 40443776, 2025).
gastrointestinal disorders (1 paper, 2023). "However, further research is needed to investigate the potential role of PCSK9 inhibitors in gastrointestinal disorders." (PMID 37350960, 2023).
head and neck tumours (1 paper, 2021).
muscular disorders (1 paper, 2024). "Together with the data observed in the present research, these results suggest the need for a comment on the possible mechanistic principles causing muscular disorders induced by PCSK9 inhibitors." (PMID 38543150, 2024).
respiratory disease (1 paper, 2024). "Fifth, even if the genetic associations with respiratory disease foretell findings in humans from inhibition of PCSK9 that have yet to be identified, the relevance of the magnitude of these effects and how to frame these in terms of absolute risk are unclear." (PMID 38198221, 2024). "The LDL-C-lowering PCSK9 genetic variants are associated with lower risk of subclinical and clinical atherosclerotic vascular disease but higher risks of respiratory diseases." (PMID 38198221, 2024). "This study provides evidence that genetic variants in PCSK9 that lower LDL-C and risk of CVD are also associated with higher risks of respiratory disease, in particular acute URTI and acute exacerbations of COPD." (PMID 38198221, 2024).
PCSK9 also shares sentences with these, for which no sentence is quoted: acute myocardial infarction (28 papers); Parkinson disease (7); Hepatitis (4); immune disorders (4); calcification (3); cardiac arrhythmia (3); chronic hepatitis C (3); dysbetalipoproteinemia (3); end-stage renal disease (3); hypertrophic cardiomyopathy (3); long QT syndrome (3); metabolism (3); transient ischemic attack (3); allergies (2); amyotrophic lateral sclerosis (2); brain cancer (2); breast tumor (2); cervical squamous cell carcinoma (2); diabetic retinopathy (2); dilated cardiomyopathy (2); Duchenne muscular dystrophy (2); essential hypertension (2); experimental autoimmune encephalomyelitis (2); glaucoma (2); immune deficiency (2); Impaired glucose tolerance (2); influenza (2); intrauterine growth restriction (2); kidney cancer (2); lipodystrophy (2).
A further 147 diseases each share a sentence with PCSK9 in 2 papers or fewer.